IL10 (interleukin 10)
Diseases named in the same sentence as IL10 in open-access papers (continued):
Sharing a sentence is not in itself a finding about the gene and the disease.
cerebral malaria (continued). "Similar transfer experiment of IL-10 producing B cells generated by non-pathogenic stimulus will determine their applicability in treatment of cerebral malaria." (PMID 23724100, 2013). "Indirect evidence points to a role for IL-10 in children with cerebral malaria." (PMID 21447146, 2011). "However, the IL-10 levels were comparable between cerebral and non-cerebral malaria." (PMID 36668942, 2023). "In the children examined in this study, cerebral malaria patients had elevated serum levels of IFN-γ, IL-1β, and IL-10 compared to uncomplicated malaria patients." (PMID 22336003, 2012). "Elevated plasma concentrations of IL-10 are detected in both mild and cerebral malaria, which is compatible with our findings, but for non-survivors of cerebral malaria a decrease in IL-10 levels was shown." (PMID 34359826, 2021). "The degree of brain swelling was independent of plasma levels of IL-1β, IL-6, IL-8, and IL-10 in children with cerebral malaria, while IL-12 and TNF were elevated in patients with more severe edema." (PMID 33391257, 2020). "Here, we identified NK cell-intrinsic STAT3 activation as vital for IL-10 production during both systemic Listeria monocytogenes (Lm) infection and following IL-15 cytokine/receptor complex (IL15C) treatment for experimental cerebral malaria (ECM)." (PMID 31552035, 2019). "Comparing the proportion of IFNγ+, IFNγ+ IL10+ and IL10+CD4+ T cells in patients with uncomplicated and severe cerebral malaria, we detected a trend towards a decreased proportion of IL10+CD4+ T cells in patients with severe cerebral malaria." (PMID 27802341, 2016). "Serum TNF, IFN-γ, IL-1β, IL-6, and IL-10 did not vary based on either TLR2 Δ22 or GTn genotype in children with cerebral malaria." (PMID 22336003, 2012). "On the other hand, the role of IL-6 in the development of cerebral malaria has not been well elucidated, as well as the role of IL-10, which may have double features during malaria infection." (PMID 31878288, 2019). "Another study reported that patients with HIV and cerebral malaria have lower median plasma levels of TNF-α and IL-10 than patients without HIV." (PMID 36692923, 2023). "Negative geotaxis and tremor are reflective of specific changes seen in cerebral malaria in WT mice infected with P. berghei ANKA, or IL‐10 KO infected with P. chabaudi, and are not seen in adult WT mice." (PMID 36131528, 2022). "In the absence of IL-10, 129 × C57BL/6 mice developed cerebral malaria when infected with 106 PbA iRBCs14." (PMID 29367729, 2018). "PTP inhibition prevented the development of neuropathology in the IL-10KO mice, evidenced by the lack of cerebral malaria symptoms exhibited by these mice, indicating that bpV(phen)-mediated protection from ECM is not IL-10 dependent." (PMID 28710387, 2017). "In fact, recent immunological analyses have shown that, unlike individuals with mild and severe non-cerebral malaria, CM patients present elevated levels of a specific cluster of cytokines, which include TGF-β, TNF-α, IL-1β and IL-10." (PMID 18769544, 2008).
AIDS (49 papers, 2009 to 2025). A syndrome resulting from the acquired deficiency of cellular immunity caused by the human immunodeficiency virus (HIV). "IL-10 has been shown to block HIV-induced TNF-α and IL-6 secretion and inhibit HIV replication, and a cohort study of 51 people with HIV suppressed on ART demonstrated decreasing plasma IL-10/TNF-α ratio to be associated with AIDS progression." (PMID 38019897, 2023). "We previously showed that pre-treatment levels of IL-10 were associated with response to therapy, as well as overall survival, in AIDS-NHL16." (PMID 35655072, 2022). "Prospective results in HIV+ patients have found high serum levels of IL-6 and IL-10 that progressively increased during the years before the diagnosis of AIDS-associated B-cell lymphoma." (PMID 30337929, 2018). "In HIV-1 infected patients, production of interleukin-10 (IL-10), a highly immunosuppressive cytokine, is associated with progression of infection toward AIDS." (PMID 25471526, 2014). "Recently, haplotypes of the IL-4 and IL-10 genes associated with AIDS progression have been reported." (PMID 20380696, 2010). "Additional IL10 variants have also been associated with disease progression to AIDS, often with inconsistent conclusions." (PMID 20976276, 2010). "IL‐10 5′A is associated with decreased IL‐10 expression that limits infection and accelerates AIDS." (PMID 38099246, 2023). "In a study involving macaques with SIV-induced encephalitis, rapid progression to Acquired Immune Deficiency Syndrome (AIDS) correlated with an increase in IL-1β, IL-2, IL-6, IL-10, and TNF-α." (PMID 34784367, 2021). "Additionally, an IL10 genotype that is associated with enhanced IL10 production was seen to be a risk factor for AIDS-NHL27." (PMID 31253857, 2019). "It has been reported that acquired immune deficiency syndrome patients with decreased levels of DHEA-S show excessive cytokine production by Th2 cells (IL-4, IL-5, IL-6, and IL-10) and suppression of other cytokines (IL-2, IFN-γ, IL-12)." (PMID 29694639, 2018). "Therefore, this approach allowed us to identify important differences involving IP-10, TNF-α, IL-6, IFN-α, and IL-10 interactions that play important roles in AIDS and are a hallmark between the two treatments here analyzed." (PMID 26684789, 2015). "Th2 cells produce cytokines like interleukin-4 (IL-4) and interleukin-10 (IL-10), which have anti-inflammatory properties but can lead to systemic AIDs when overactivated." (PMID 40677716, 2025). "Clerici and Shearer observed that the progression of HIV infection in AIDS is characterized by the loss of IL-2 and IFN-γ production and the increase in IL-4 and IL-10." (PMID 39062756, 2024). "Serum IL-6/IL-10 ratio was also used to evaluate the severity of pneumocystis pneumonia in HIV/AIDS patients." (PMID 36371539, 2022). "Many studies have suggested that anti-inflammatory cytokines including IL-10, are associated with the KSHV infection and/or AIDS KS development." (PMID 32998419, 2020). "More recently, studies have shown an elevated level of serum IL-10 in visceral AIDS-KS patients compared to HIV-positive individuals and classic KS patients." (PMID 32998419, 2020). "On the other hand, the Th2-specific cytokines, i.e., IL-4, IL-5, IL-6, IL-10, and IL-13, are associated with disease progression and lead to the progression of HIV infection to AIDS." (PMID 31641392, 2019). "Among these, IL-10 was seen to be increasing closer to diagnosis in those with AIDS-KS and IL-12p70 was decreasing, both of which would be consistent with reduced TH cell differentiation." (PMID 33521162, 2018). "During HIV chronic infection, the presence of IL-6, IL-10, and TNF-α are associated with poor prognosis and progression to AIDS because they contribute to the chronic activation of B-cells." (PMID 30337929, 2018). "In conclusion, our data suggest that detection of plasma IL-8 levels and IL-6/IL-10 ratio combined with LDH and HBDH can predict the severity of PCP risk of death in AIDS patients with PCP." (PMID 27579328, 2016).
AIDS (continued). "IL-10 levels were almost similar in CT/AIDS and OT patients but low when compared with CHR individuals." (PMID 25352834, 2014). "IL-10 levels in response to TLA were almost similar in CT/AIDS and OT patients but low when compared with CHR individuals." (PMID 25352834, 2014). "Especially, there are high levels of IL-6 and IL-10 in body cavity effusions from AIDS patients with PEL." (PMID 24587336, 2014). "All these indicate that OT and CT/AIDS patients produced low levels of IL-10 (Th2 response) and IFN-γ (Th1 response)." (PMID 25352834, 2014). "All these data together indicate that OT and CT/AIDS patients produced low IL-10 (Th2 response) and IFN-γ (Th1 response)." (PMID 25352834, 2014). "The IL-6, IL-10 and G-CSF levels were associated with hospital mortality in the HIV/AIDS septic group; however, the CRP levels and the surrogates of innate immune activation (cytokines) were similar among HIV/AIDS and non-HIV septic patients." (PMID 23874739, 2013). "In our study, three cytokines (IL-6, IL-10 and G-CSF) were associated with hospital mortality in HIV/AIDS septic patients." (PMID 23874739, 2013). "Higher levels of IL-6, IL-10 and G-CSF were associated with hospital mortality among HIV/AIDS septic patients." (PMID 23874739, 2013). "The serum concentration of IL-10 increases in HIV-positive patients with progression to AIDS, and decreases with highly active antiretroviral therapy (HAART)." (PMID 23374857, 2013). "Opportunistic infections, especially present at the late stages of the disease, trigger IL-10 production and IL-10 production from patients with AIDS has been reported to decrease in vitro HIV-1 replication and TNFα production." (PMID 20380696, 2010). "Fine mapping coupled with analysis of gene expression and function should help reveal the immunological importance of the IL10 gene family to HIV-1/AIDS." (PMID 20976276, 2010). "Dendritic cells In HIV/AIDS are functionally impaired, producing less IL-12 and more IL-10, disrupting the IL-12/IFN-gamma signaling pathway and contributing to problems with adaptive immunity." (PMID 19680452, 2009). "Given that high levels of secreted CD14 have been associated with impaired responses to LPS, it has been proposed that the release of general immunosuppressant IL-10 by monocytes facilitates the progression to AIDS." (PMID 19486514, 2009). "Increased IL-10 has been shown to play a role in this impaired innate immune response in AIDS patients." (PMID 19680452, 2009). "Significantly increased IL-10 levels were also observed in HIV/AIDS patients compared with healthy controls." (PMID 19486514, 2009). "Thus, plasma levels of PD-L1-expressing EVs and IL-10 hold promise as effective prognostic biomarkers in AIDS-NHL." (PMID 35655072, 2022). "Overview of the role of Tr1 and IL-10-producing CD4+ T cells in AIDs and IBD." (PMID 36389662, 2022). "Similarly to IL6 and IL10, circulating BAFF levels correlate with complete remission rate, overall survival and progression-free survival in AIDS-associated NHL." (PMID 35008292, 2021). "Similarly, studies have demonstrated the involvement of elevated levels of cellular cytokines including IL-10 in the pathogenesis of KSHV-associated diseases, including PEL and MCD in patients with HIV/AIDS." (PMID 32998419, 2020). "Furthermore, although the relationship between IL-6 and IL-10 is unclear in HIV+ subjects, these cytokines appear to be intrinsically linked to infection progression and AIDS onset." (PMID 27214135, 2016). "Plasma IL-8, LDH, and HBDH levels and IL-6/IL-10 ratio could be helpful for early evaluation of the severity and predicting fatal outcomes in AIDS PCP patients." (PMID 27579328, 2016). "Taken together with our observations, these results suggest a strong association of high IL-6 and IL-10 levels with progression through the stages of HIV infection to AIDS regardless of the patients’ progression group." (PMID 27214135, 2016).
AIDS (continued). "Indeed, peripheral blood mononuclear cells (PBMCs) from HIV-1-positive patients produce high levels of IL-10, whose level increases as the patient progresses toward AIDS." (PMID 25471526, 2014). "At the onset of AIDS, T-cell apoptosis is dramatically increased and opportunistic infections are very frequent, resulting in an enhanced apoptotic cell clearance by IL-10-deactivated macrophages." (PMID 20380696, 2010). "Furthermore, up-regulation of IL-10 production in HIV/AIDS patients has been correlated with increased levels of monocyte-secreted myeloid differentiation-2 and soluble CD14; both proteins are key molecules in the immune recognition of gram-negative bacterial lipopolysaccharide (LPS)." (PMID 19486514, 2009). "In prior work, we observed that serum IL10 levels are elevated over a period of years (1–5 years) preceding AIDS-NHL diagnosis, as well as after AIDS-NHL diagnosis." (PMID 31253857, 2019). "IFN-γ, sIL-2Rα, sIL-6R, IL-10, IP-10, TNF-α, MCP-1, sCD14, BLC-BCA1 and sTNFR-2 were found to be higher in the subsequent AIDS-KS cases than those unaffected." (PMID 33521162, 2018). "sIL-2Rα, sIL-6R, IL-10, IP-10, MCP-1, TNF-α, eotaxin, BLC-BCA1, CD27 and sTNFR-2 were all statistically significantly higher in AIDS-KS than controls." (PMID 33521162, 2018). "Those with statistically significantly higher values in the AIDS-KS cases were IFN-γ, MCP-1, IFN-γ, sIL-6R, sIL-2Rα, IL-10, BLC-BCA1, CD27, sTNFR-2, sCD14, TNF-α, and IP-10." (PMID 33521162, 2018). "IL-6, IL-10 and G-CSF are biomarkers that can be used to predict prognosis and outcomes in HIV/AIDS septic patients." (PMID 23874739, 2013). "In the present study, we examined how baselinies plasma levels of CD20+ extracellular vesicles (EVs) relate to these previously characterized biomarkers of AIDS-NHL, such as IL-10, CXCL13, IL-10, BAFF, sCD14, sTNF-RII, sIL-2Rα/sCD25, IL-18, and CCL12-MCP-129–31." (PMID 40646161, 2025). "The maximum frequency of CD4+ T cells expressing IL-4 was seen in HIV-infected individuals without AIDS, whereas the rate of IL-10-producing CD4+ T cells was highest in patients with AIDS." (PMID 39062756, 2024). "Many markers mirrored general trends in both groups, indicating that the changes are normal and not due to AIDS-KS development, however for sCD14, IL-12p70, IL-10 and IL-8, the trends were very different from the trends in the control group." (PMID 33521162, 2018). "IL-10 production has previously been shown to increase in Mycobacterium avium–stimulated monocytes from HIV-infected patients, with the highest expression observed in patients with advanced AIDS." (PMID 23303806, 2013). "The HIV/AIDS non-surviving patients presented significantly higher levels of IL-6, IL-10 and G-CSF when compared with the survivors; however, the cytokine levels were similar between the HIV and non-HIV septic patients." (PMID 23874739, 2013). "Therefore we calculated the Spearman correlation coefficients for plasmatic levels of IL-10, IL-22 and CRP and disease progression as defined by patients' viral load, CD4 cell counts, and AIDS-defining conditions." (PMID 20211031, 2010). "In HIV-infected patients, the amount of IL-10, but not IL-4, increases significantly in patients with AIDS." (PMID 20380696, 2010). "Similarly, higher levels of IL-10 in AIDS patients with compared to those without an IBD-like pattern were suggested by a trend towards significance in the present study." (PMID 21125014, 2010). "In addition, the IL-10 and G-CSF levels were higher in the HIV/AIDS non-survivors in our study." (PMID 23874739, 2013).
food allergy (49 papers, 2010 to 2025). Gastrointestinal disturbances, skin eruptions, or shock due to allergic reactions to allergens in food. "We should note that the exacerbation of PSA due to temporary IL-10 administration and the loss of the capability to develop a food allergy in Il10-/- mice indicate that IL-10 is a crucial factor for the immediate activation of MCs." (PMID 34067047, 2021). "Food allergy is associated with the dysregulation of Th2 cytokines, such as IL-4 and IL-10, suggesting that the Th2 response is critical in food allergy." (PMID 34650564, 2021). "Our previous studies showed that TTP bound IL-10 mRNA to induce IL-10 decay in B cells of an experimental food allergy study, but the underlying mechanism remains to be further investigated." (PMID 34926702, 2021). "Clinical study indicates that IL-10 gene polymorphism is associated with food allergy and lower serum IL-10 levels." (PMID 28086216, 2017). "Furthermore, while both IL-33 and IL-10 were independently required for full MC responsiveness during food allergy, IL-10 deficiency further decreased MC responses in ST2-/- mice." (PMID 39935481, 2025). "To therefore determine the role of the IL-33/ST2 axis in this pathway, we assessed the effects of IL-10 on IgE-mediated MC activation and food allergy development in wild-type (WT) and ST2-/- mice." (PMID 39935481, 2025). "Our findings also further confirm the importance of IL-10 in regulating MC responses during the development of food allergy." (PMID 39935481, 2025). "IL-10 promoted the activation and function of both IgE-activated and IL-33-stimulated MCs, leading to enhanced MC responses during food allergy, passive anaphylaxis, and type 2 inflammation." (PMID 39935481, 2025). "To look at this, we analyzed intracellular IL-4 and IL-10 in TFR cells by flow cytometry in the food allergy response." (PMID 39377224, 2024). "The analysis of peripheral blood mononuclear cells (PBMCs) from children with food allergy highlighted that butyrate increases IL-10, IFN-γ, and FOXP3 expression by epigenetic modifications." (PMID 35565735, 2022). "IL-10 has pleiotropic effects on mast cell effector function, including the ability to promote IgE-mediated food allergy." (PMID 36142776, 2022). "The enhancement of IgE-mediated mast cell activation by IL-10 is critical for the development of food allergy in mouse models." (PMID 36077487, 2022). "The development of food allergies in Il10-/- mice was complemented with the transfer of WT BMMCs, suggesting that the IL-10 derived from MCs is crucial for the pathology of food allergies." (PMID 34067047, 2021). "IL-10 is critical in providing protective immune cell activation and protective inflammation involved in the development of food allergies and septic defense." (PMID 32098318, 2020). "For the remainder of this review, we focus on recent findings in inflammatory bowel diseases, food allergy, cancer, autoimmunity, and autoinflammation, and then we close with special attention to novel effects of IL-10 and TGF-β1." (PMID 32098318, 2020). "Our observations of elevated IL-10 by wheat allergens in the AF model further supports a pro-allergenic role for IL-10 in the mouse models of food allergy where allergens are administered via the skin." (PMID 32369940, 2020). "IL-10 was demonstrated to be essential for the development of food allergy by inducing mucosal mast cell expansion and activation." (PMID 31349704, 2019). "In contrast, mice on soy-free diet had significantly higher levels of IL-10 and were protected from food allergy development." (PMID 30453476, 2018). "In our previous studies, we found that significantly lower frequency of IL-10+ B cells was observed in mice with food allergy." (PMID 28373650, 2017). "Our previous work also found that IL-10-producing B cells were less in the intestine of mice with food allergy." (PMID 28086216, 2017).